ALK (ALK receptor tyrosine kinase)
Diseases named in the same sentence as ALK in open-access papers (continued):
Sharing a sentence is not in itself a finding about the gene and the disease.
lung cancer (continued). "Data from clinical trials testing combinations of TKIs and IO for efficacy in EGFR and ALK-driven lung cancer patents demonstrate modest increases in response rates as compared to single agent IO." (PMID 34001994, 2021). "Multiple oncogene fusions are currently targeted in lung cancer treatment, such as those involving ALK, RET, NTRK and ROS1 among many others." (PMID 34680187, 2021). "One possible reason is the expression of tissue factor (TF) gene was elevated in around 41.7% of ALK-positive, but only 11.5% of ALK-negative tissue in patients with lung cancer (p = 0.015)." (PMID 34205695, 2021). "For example, a small subset of lung cancer patients with rearrangements of ALK or ROS1 genes are sensitive to ALK inhibitors." (PMID 33738250, 2021). "Around 3–7% of patients with non-small cell lung cancer (NSCLC), which represent 85% of diagnosed lung cancers, have a rearrangement in the ALK gene that produces an abnormal activity of the ALK protein cell signaling pathway." (PMID 33659043, 2021). "in lymphoma and lung cancer PD-L1 expression is elevated by the ALK (anaplastic lymphoma kinase) through STAT3 activation." (PMID 34185141, 2021). "The fusion rearrangement of anaplastic lymphoma kinase (ALK) gene is an important feature of brain metastasis in lung cancer." (PMID 33091333, 2021). "Targeted treatment of metastatic ALK‐rearranged non‐small cell lung cancer with ALK inhibitors leads to higher response rates and improves progression‐free survival (PFS) relative to conventional chemotherapy regimens." (PMID 33565277, 2021). "Brigatinib is approved in multiple countries for treatment of patients with ALK-positive non–small cell lung cancer." (PMID 33742299, 2021). "Suprisingly, we firstly reported osteoclast differentiation in ALK-positive lung cancer in the world." (PMID 34234236, 2021). "As with EGFR-mutant lung cancer, a remaining question with highly effective ALK inhibitors is when to use them alone versus in combination with radiotherapy for intracranial metastases at diagnosis." (PMID 34859233, 2021). "As they share the same essential growth driver due to constitutively activated ALK, we investigated the applicability of ALK inhibitors, such as in conventional therapy of lung cancer harboring EML4-ALK, to thyroid cancer." (PMID 33878728, 2021). "YAP also confers resistance to chemotherapeutic agents such as epidermal growth factor receptor (EGFR)-tyrosine kinase inhibitors (TKIs), and anaplastic lymphoma kinase (ALK) inhibitors in lung cancer." (PMID 34202980, 2021). "Anaplastic lymphoma kinase (ALK) rearrangements are drivers of a subset of non‐small cell lung cancer (NSCLC)." (PMID 33960639, 2021). "Immunohistochemical staining showed that SPP1 staining pattern in lung cancer was cytoplasmic, and the average scores for 5 ALK-positive and 5 ALK-negative lung cancer samples were 6.8 ± 1.095 and 0.8 ± 0.837, respectively." (PMID 34234236, 2021). "The CRISPR/cas9 system provides unique opportunities to test the efficacy of targeted therapies, investigate mechanisms of drug resistance, and to test newer immune-based therapeutic strategies for ALK rearranged lung cancer in preclinical in vivo models." (PMID 33806977, 2021). "A previous study also reported that plasma exosomal miR-320d is upregulated in progressive disease compared with the partial response of immunotherapy in EGFR/ALK wild-type advanced nonsmall cell lung cancer." (PMID 34503068, 2021). "Until now, the updated CAP/IASLC/AMP molecular testing guideline for lung cancer recommended IHC as an equivalent alternative to FISH for ALK testing." (PMID 33565277, 2021). "Taking as an example lung adenocarcinoma accounting for the highest proportion of lung cancer, the rate of functional driver gene mutations including EGFR, KRAS and rearrangement of ALK or ROS1, is approximately 60%." (PMID 34814861, 2021).
lung cancer (continued). "ALK-rearranged lung cancer is a unique molecular subgroup with a high sensitivity to ALK inhibitors and mutually exclusive with other well-known oncogenic mutations (EGFR or KRAS)." (PMID 33946969, 2021). "Despite impressive and durable responses, nonsmall cell lung cancer (NSCLC) patients treated with anaplastic lymphoma kinase (ALK) inhibitors (ALK‐Is) ultimately progress due to development of resistance." (PMID 34058070, 2021). "In this study, total of 521 tumor specimens from Chinese patients with lung cancer were screened for ALK fusion by immunohistochemistry (IHC) and confirmed by fluorescence in situ hybridization (FISH)." (PMID 34234236, 2021). "This study investigated the frequencies, clinical characteristics, therapeutic efficacies, and genetic profiles of lung cancer patients with EGFR and ALK co-mutations." (PMID 34654390, 2021). "Different classes of ALK tyrosine kinase inhibitors (TKI) are available but used exclusively for EML4-ALK (+) lung cancers." (PMID 33466277, 2021). "The obvious increase of SPP1 mRNA and protein in ALK-positive lung cancers is attracting considerable interest." (PMID 34234236, 2021). "Crizotinib was introduced based on the phase 3 Profile 1014 study as a standard of treatment in patients with ALK-positive lung cancer." (PMID 33435596, 2021). "Immunohistochemistry analyzed the cellular localization of p-STAT6, p-JAK2, and ALK in EML4-ALK-positive lung cancer tissues." (PMID 34090412, 2021). "For example, 4% to 7% of patients with non–small cell lung cancer (NSCLC) have overexpression of anaplastic lymphoma kinase (ALK)." (PMID 33763370, 2021). "The biological potential of heterocycles possessing β-amino acid motifs also has found application in searching for new anaplastic lymphoma kinase (ALK) inhibitors for the treatment of non–small-cell lung cancer (NSCLC)." (PMID 33467741, 2021). "Although it is seen in only a small percentage of lung cancers, it is an important predictor of response to anti-ALK targeted therapies." (PMID 32876329, 2021). "Our finding revealed deregulation of PI3K/AKT signaling pathway, EGFR tyrosine kinase inhibitor resistance, non-small cell lung cancer and osteoclast differentiaton in ALK-positive lung cancer." (PMID 34234236, 2021). "Deregulation of PI3K/AKT signaling pathway in ALK-positive lung cancer was demonstrated by WES analysis, and significantly increased mRNA of ALK, ROS1, MET, SPP1 and PI3K signaling pathway was identified by NanoString assay." (PMID 34234236, 2021). "Another gene of particular importance in the NSCLC is anaplastic lymphoma kinase (ALK) which is translocated in 3–7% of lung cancer cases." (PMID 36046142, 2021). "The phase 3 clinical trial ASCEND-4 compared ceritinib with chemotherapy as the first-line treatment in patients with advanced lung cancer and ALK rearrangement." (PMID 33435596, 2021). "We further analyzed mRNA expression of 67 genes in the same 5 ALK-positive lung cancer samples and the corresponding pericarcinous (normal) tissues by NanoString assay." (PMID 34234236, 2021). "Our data also described 42.9% of patients with ALK-positive lung cancer was found at stage IV at diagnosis and the median overall survival was only 12 M in patients who did not receive targeted therapy, this finding is consistent with previous reports." (PMID 34234236, 2021). "Targeted kinase inhibitors improve the prognosis of lung cancer patients with ALK alterations (ALK+)." (PMID 34876698, 2021). "Since the first descriptions of ALK rearrangements in lung cancer, prevalence estimates for this rearrangement have ranged relatively broadly from <2–13%." (PMID 34786182, 2021).
lung cancer (continued). "Our network meta-analysis provides updated information and a proposed ranking for PFS, OS, ORR, and grade 3–5 AEs for different ALKIs for treatment-naïve ALK-positive lung cancer patients." (PMID 33921762, 2021). "Still, even within oncogene-defined subsets of lung cancers driven by mutant EGFR or ALK, the individual responses to targeted TKIs ranges widely." (PMID 33485341, 2021). "Our group has recently profiled a large Nova Scotian lung cancer patient cohort for major driver mutations in lung cancer (EGFR, ALK, KRAS, BRAF, and PIK3CA)." (PMID 33956842, 2021). "Most patients treated with anaplastic lymphoma kinase (ALK)‐tyrosine kinase inhibitors for ALK‐positive non‐small cell lung cancer (NSCLC) develop resistance, leading to metastasis, with progression to the central nervous system (CNS) being a primary concern." (PMID 33960745, 2021). "In our study, 43.3% of cases showed acinar-predominant growth patterns, and 21.7% of cases showed solid-predominant growth patterns in the patients with ALK-positive lung cancer." (PMID 34530849, 2021). "Kinases represent a major class of oncogenes, and two well-known examples of cancer-promoting kinase gene fusions are the BCR-ABL1 fusion in leukemia patients and fusion of ALK to various other proteins in lung carcinomas and mesenchymal tumors." (PMID 33809651, 2021). "SCLC transformation from NSCLC has rarely been observed in EGFR-wild type lung cancers or during ALK-targeted therapy and programed cell death-1 (PD-1/L)-directed immunotherapy." (PMID 35582610, 2020). "We started to wonder if such pharmacologic functions of NHERF1 can also be observed in lung cancers, especially in ALK positive lung cancer cells." (PMID 32164629, 2020). "Crizotinib is a low molecular weight, orally available TKI that inhibits ROS1, MET and ALK and is considered the gold standard first-line treatment with demonstrated significant activity for lung cancers harbouring ROS1 gene rearrangements." (PMID 33172113, 2020). "The ROS1 protooncogene is a receptor tyrosine kinase similar to ALK and re-arrangements of ROS1 have been described as “driver mutations” in lung cancers." (PMID 32283832, 2020). "The expression level of NHERF1 in ALK-translocated NSCLC was significantly higher than that in other lung cancer tissues." (PMID 32164629, 2020). "In our recent study, we have demonstrated that ceritinib, an anaplastic lymphoma kinase (ALK)-positive inhibitor for lung cancer treatment, is able induce breast cancer stem cell sphere explosion and death." (PMID 32764489, 2020). "McCoach and collaborators performed a survey of a laboratory cohort of ALK-positive lung cancer patients whit ctDNA tested by G360 assay to determine the clinical utility of plasma-based comprehensive genomic profiling." (PMID 32726941, 2020). "The three studies suggested that the incidence of driver gene mutations in NSCLC patient is high, and lung cancer driver genes, such as EGFR, ALK, and RET are risk factors for brain metastasis in advanced NSCLC patients." (PMID 33537237, 2020). "In newly diagnosed, advanced ALK-positive lung cancer, the incidence of BM varies from 20% to 30%, and the overall incidence of postdiagnosis BM increases over time, standing at 23.8% after 1 year, 45.5% after 2 years and 58.4% after 3 years." (PMID 32640547, 2020). "Next, we used the programmable knockdown capacity of the Cas13a machinery to target ALK RNA in EML4-ALK fusion transcripts in H3122 lung cancer cells, with the goal of decreasing cell viability and providing proof-of-principle of a novel therapeutic approach." (PMID 33255340, 2020). "Since ALK fusion gene positive lung cancer was first reported in 2007,18 various ALK‐TKIs have been developed and clinically used in various countries all over the world." (PMID 31943796, 2020).
lung cancer (continued). "All laboratories that examine lung cancer specimens are advised to test for mutations in a minimum of one set of genes, namely, epidermal growth factor receptor (EGFR), ALK, and ROS1." (PMID 33425389, 2020). "In lung cancer treatment, gene sequencing has been performed mainly as a companion diagnostic approach for identifying mutations in genes such as EGFR and anaplastic lymphoma kinase (ALK) and subsequent selection of molecular target drugs." (PMID 33233456, 2020). "Previous studies have shown that qRT-PCR is an effective method for detecting ALK rearrangement using cytology samples from patients with primary lung cancer." (PMID 33425389, 2020). "Different liquid biopsy methods can be used to assess the presence of ALK rearrangements in lung cancer patients." (PMID 33207619, 2020). "In this retrospective study, we report 19 lung cancer patients who had inconsistent intersample ALK FISH results obtained from multiple tumor samples collected at different time points during their clinical courses." (PMID 32674491, 2020). "Five ALK inhibitors including crizotinib, ceritinib, alectinib, brigatinib and lorlatinib have been approved to date for the treatment of ALK-positive lung cancer in the European Union and the United States." (PMID 33171712, 2020). "From this study, a high level of NHERF1 expression was found in lung cancer tissues, especially in patients diagnosed with ALK-translocation." (PMID 32164629, 2020). "From a group of 384 patients with lung cancer tested two or more times by FISH to assess ALK status, we observed inconsistent intersample results in about 5% of patients." (PMID 32674491, 2020). "In conclusion, we propose a new ALK-BPI score as a prognostic tool that can be easily applied for ALK-positive lung cancer patients with BM in daily clinical practice, and that has at least the same, if not better, prognostic value as the Lung-molGPA system." (PMID 32640547, 2020). "This dataset was a lung cancer cohort, containing normal individuals, those with epidermal growth factor receptor (EGFR) mutations, anaplastic lymphoma kinase (ALK) mutations, RAS mutations and wild type lung adenocarcinoma at different stages." (PMID 32708433, 2020). "To date, only one research group has reported discrepant intersample results for ALK status in lung cancer patients." (PMID 32674491, 2020). "Although these mutations and rearrangements of EGFR, ALK, and ROS1 occur in a higher number of lung cancer cases, several other kinases show rare mutations and a wide range of different fusion genes and associated partners." (PMID 35582610, 2020). "ALK inhibitors bind to ALK‐tyrosine kinase and show a high response rate to ALK‐rearranged lung cancer." (PMID 31943796, 2020). "The Ampliseq RNA lung cancer panel, allowing the analysis of about 70 fusions involving ALK, ROS1, RET and NTRK1 is one of the most diffuse." (PMID 32726941, 2020). "For instance, EGFR, ALK, and ROS1 tyrosine kinase inhibitors against tumors with EGFR mutations, ALK fusions, and ROS1 fusions respectively, are already in use as standard treatments in lung cancer in clinical settings." (PMID 33264103, 2020). "A major limitation of the Lung-molGPA study is that available treatment options for ALK-positive lung cancer patients were also limited in this cohort (patients diagnosed between 2006 and 2014)." (PMID 32640547, 2020). "The molecular characterization of lung adenocarcinoma has revolutionized the treatment of lung cancer with the discovery of targetable genetic alterations such as EGFR mutations and ALK gene rearrangements." (PMID 32149365, 2020). "The different ALK-positive lung cancers showed variations in their Bcl-xL and Mcl-1 expression profiles." (PMID 31900393, 2020). "ALK FISH analyses of multiple specimens occasionally yield inconsistent intersample results in lung cancer patients, posing clinical challenges requiring intensive analysis of all potential causative pre- and post- analytic factors." (PMID 32674491, 2020).
lung cancer (continued). "This needs to be confirmed in other cancers because it was observed under specific settings: ALK-rearranged lung cancer cell lines treated with ALC." (PMID 31900393, 2020). "Another molecular target in treating lung cancer is the anaplastic lymphoma kinase (ALK) fusion gene." (PMID 32770960, 2020). "Translocations, which can result from errors in repairing DSBs, are also common in lung cancers, with gene fusions in the tyrosine kinases ALK and ROS1 being the first identified, targetable driver rearrangements in NSCLC." (PMID 32850380, 2020). "The high frequency of negative results was expected, as we test all new patients with lung cancer by FISH for ALK status, and the frequency of ALK rearrangement in lung cancer ranges from 3 to 7% in various studies." (PMID 32674491, 2020). "We consider combinatorial therapy against ALK and YAP1 to be a promising therapy that enhances treatment effects in ALK-rearranged lung cancer." (PMID 31900393, 2020). "As expected, the Japanese population had higher rates of EGFR and ALK-positive lung cancer (31 and 6%, respectively in 2015–2017)." (PMID 33704175, 2020). "The present results provide a promising treatment that achieves sustained remission from ALK-positive lung cancer." (PMID 31900393, 2020). "In clinical practice, patients with anaplastic lymphoma kinase (ALK)-rearrangement–positive non–small-cell lung cancer commonly receive sequential treatment with ALK tyrosine kinase inhibitors." (PMID 33171712, 2020). "We propose the ALK-BPI scoring system for patients with ALK-positive lung cancer with BM as a robust and easy-to-use prognostic clinical tool." (PMID 32640547, 2020). "NHERF1 expression in ALK positive lung cancer cells was regulated by ALK activities, and was in return able to alter the sensitivity to crizotinib." (PMID 32164629, 2020). "Sequential treatment furthermore raises the question of rebiopsy in patients with progressive ALK-positive lung cancer." (PMID 33171712, 2020). "Relapse is a limitation for the efficacy of the anaplastic lymphoma kinase (ALK)-inhibitor alectinib in ALK-rearranged lung cancer." (PMID 31900393, 2020). "Accordingly, the ALK inhibitor, Crizotinib, was proven to be an effective, and safe treatment for lung cancer patients harboring EML-ALK54, leading to the quick approval of the drug by the FDA." (PMID 32651364, 2020). "Nevertheless, the jury is still out regarding biomarker-driven treatment decisions in ALK-positive lung cancer, and investigations in this area are ongoing." (PMID 33171712, 2020). "Compared with chemotherapy, crizotinib showed a better therapeutic effect in ALK-positive lung cancer." (PMID 33381185, 2020). "High cytoplasmic RAP1 can increase cisplatin resistance of NSCLC combined with increased NF-κB activity, and RAS-RAF-MEK-ERK signaling was a vital pathway that mediates ALK positive tumor cell survival in lung cancer." (PMID 33005178, 2020). "In a recent study on ALK FISH-positive lung cancer, patients with canonical fusion partners involving EML4 were found to have better overall survival (20.6 months vs. 5.4 months, p < 0.01) than those with noncanonical ALK fusions." (PMID 33019710, 2020). "Advances in DNA sequencing technology revealed the driver mutations in lung cancers at the genes including EGFR, ROS1, BRAF, ALK, and KRAS." (PMID 33276627, 2020). "A recent study indicated that the RAS-RAF-MEK-ERK signaling pathway determines the ALK inhibitor response in ALK-positive lung cancer, but still needs further investigation." (PMID 32727606, 2020). "Although concomitant EGFR mutations and ALK fusion in lung cancer had once been considered to be mutually exclusive, the coexistence of EGFR mutations and ALK fusion in patients with lung cancer has been detected in a series of studies in recent years." (PMID 33520689, 2020). "YAP1 expression mediated the survival of ALK-rearranged lung cancer cells treated with alectinib by a mechanism involving pro-apoptotic protein regulation." (PMID 31900393, 2020).